MAGI2-AS3 (MAGI2 antisense RNA 3)
Synonyms: ENST00000414797
Gene: Long non-coding RNA gene on chromosome 7 (79,452,845 to 79,471,217, forward strand). Ensembl gene ENSG00000234456.
Diseases named in the same sentence as MAGI2-AS3 in open-access papers:
MAGI2-AS3 is named in the same sentence as 5 diseases in open-access papers, as found by Europe PMC text mining. Sharing a sentence is not in itself a finding about the gene and the disease. The quoted sentences say what the papers report.
breast carcinoma (1 paper, 2024). "Many studies have shown that MAGI2-AS3 is a tumor suppressor gene in breast cancer." (PMID 38978021, 2024).
MAGI2-AS3 also shares sentences with these, for which no sentence is quoted: bladder cancer (1 paper); cancer (1); glioma (1); tumor (1).